ITGB3BP (integrin subunit beta 3 binding protein)
Description:
Transcription coregulator that can have both coactivator and corepressor functions. Isoform 1, but not other isoforms, is involved in the coactivation of nuclear receptors for retinoid X (RXRs) and thyroid hormone (TRs) in a ligand-dependent fashion. In contrast, it does not coactivate nuclear receptors for retinoic acid, vitamin D, progesterone receptor, nor glucocorticoid. Acts as a coactivator for estrogen receptor alpha. Acts as a transcriptional corepressor via its interaction with the NFKB1 NF-kappa-B subunit, possibly by interfering with the transactivation domain of NFKB1. Induces apoptosis in breast cancer cells, but not in other cancer cells, via a caspase-2 mediated pathway that involves mitochondrial membrane permeabilization but does not require other caspases. May also act as an inhibitor of cyclin A-associated kinase. Also acts a component of the CENPA-CAD (nucleosome distal) complex, a complex recruited to centromeres which is involved in assembly of kinetochore proteins, mitotic progression and chromosome segregation. May be involved in incorporation of newly synthesized CENPA into centromeres via its interaction with the CENPA-NAC complex.
Synonyms: CENP-R; CENPR; NRIF3; HSU37139; TAP20
Tractability: PROTAC: UniProt records ubiquitination sites on it; ubiquitination databases record sites on it.
Gene: Protein-coding gene on chromosome 1 (63,320,884 to 63,593,721, reverse strand). Ensembl gene ENSG00000142856.
Subcellular location: Nucleus (Isoform 1); Chromosome, centromere; Chromosome, centromere, kinetochore; Nucleus (Isoform 2); Nucleus (Isoform 3); Cytoplasm; Cytoplasm (Isoform 4)
Subcellular location (Human Protein Atlas): Nucleoplasm
Pathways (Reactome):
Cell Cycle: Amplification of signal from unattached kinetochores via a MAD2 inhibitory signal; Deposition of new CENPA-containing nucleosomes at the centromere; EML4 and NUDC in mitotic spindle formation; Mitotic Prometaphase; Resolution of Sister Chromatid Cohesion; Separation of Sister Chromatids
Signal Transduction: NRIF signals cell death from the nucleus; RHO GTPases Activate Formins
Gene Ontology:
Molecular function: protein binding
Biological process: cell adhesion; chromosome segregation; signal transduction; CENP-A containing chromatin assembly; regulation of DNA-templated transcription
Cellular component: inner kinetochore; nucleoplasm; cytoplasm; cytosol; membrane; nucleus; chromosome, centromeric region
Genetic constraint (gnomAD): Loss-of-function variants: 2 observed, 1.94 expected, observed/expected ratio (o/e) 1.03, 90% interval 0.37 to 1.88. That is too few expected variants to judge how well the gene tolerates losing a copy. Missense variants: 4 observed, 2.18 expected, observed/expected ratio (o/e) 1.83, 90% interval 0.72 to 1.95.
Homologues: Orthologues: chimpanzee ITGB3BP (99% identical), macaque ITGB3BP (88% identical), dog ITGB3BP (73% identical), rabbit ITGB3BP (66% identical), mouse Itgb3bp (64% identical), guinea pig ITGB3BP (63% identical), rat Itgb3bp (60% identical).
Diseases named in the same sentence as ITGB3BP in open-access papers:
ITGB3BP is named in the same sentence as 24 diseases in open-access papers, as found by Europe PMC text mining. Sharing a sentence is not in itself a finding about the gene and the disease. The quoted sentences say what the papers report.
breast carcinoma (4 papers, 2013 to 2022). "Studies have shown that the integrin subunit β3‐binding protein (ITGB3BP) is significantly up‐regulated via the TGF‐β pathway, promoting the metastasis and invasion of breast cancer cells under hypoxic conditions, and is also an important element leading to poor breast cancer prognosis." (PMID 34953037, 2022). "Furthermore, ITGB3BP and DIF-1 complexes selectively control cell apoptosis of breast cancer by regulating FASTKD2." (PMID 33974527, 2021).
glioma (3 papers, 2021 to 2025). A benign or malignant brain and spinal cord tumor that arises from glial cells (astrocytes, oligodendrocytes, ependymal cells). "It was reported that ITGB1BP1 can promote the tumor cell migration and invasion, and ITGB3BP was associated with poor prognosis of glioma." (PMID 40731028, 2025). "Our study revealed that the overexpression of ITGB3BP was associated with the molecular and clinical characteristics of malignancy and predicted poor prognosis in glioma." (PMID 34953037, 2022). "The main aim of this study was to determine the prognostic and diagnostic value of ITGB3BP in glioma." (PMID 34953037, 2022). "Therefore, we queried the original data for survival time and survival status from the public databases and incorporated them into the meta‐analysis to obtain more evidence to support our research results that ITGB3BP is a risk factor for glioma patients." (PMID 34953037, 2022). "Consistently, through univariate, multivariate and ROC analyses, we concluded that ITGB3BP could be used as an independent predictive factor for the prognosis of glioma, with a specific diagnostic value." (PMID 34953037, 2022). "Moreover, ITGB3BP can be considered an independent risk factor for poor prognosis and has great predictive value for the prognosis of glioma." (PMID 34953037, 2022). "Subsequently, ROC curves were plotted to determine whether the expression level of ITGB3BP has clinical diagnostic value for glioma." (PMID 34953037, 2022). "Gene Set Enrichment Analysis results showed that ITGB3BP contributes to the poor prognosis of glioma by activating tumour‐related signalling pathways." (PMID 34953037, 2022). "Our findings provide the first evidence that the up‐regulation of ITGB3BP correlates with poor prognosis in human glioma." (PMID 34953037, 2022). "To clarify the impact of ITGB3BP on the survival prognosis of patients with glioma, we further used a meta‐analysis based on publicly available data for verification." (PMID 34953037, 2022). "First, to fully understand the specific mechanism of action of ITGB3BP in the development and progression of glioma, we need to consider various clinical factors, such as the specific treatment of patients." (PMID 34953037, 2022). "Meta‐analysis results also further confirmed that abnormally high expression of ITGB3BP can lead to a decline in the survival rate of patients with glioma." (PMID 34953037, 2022). "Although our current results have increased our understanding of the relationship between ITGB3BP and glioma, this study still had some limitations." (PMID 34953037, 2022). "As predicted, the mRNA expression level of ITGB3BP in glioma cell lines and tissues was significantly up‐regulated compared to that in the corresponding normal cell lines (HA) and normal tissues." (PMID 34953037, 2022). "To determine the expression level of ITGB3BP in glioma, we first analysed the mRNA expression of ITGB3BP in the GEPIA database." (PMID 34953037, 2022). "Further, we confirmed by RT‐qPCR that ITGB3BP expression was significantly increased in glioma cells and tissues." (PMID 34953037, 2022). "The pooled HR and 95% CI of ITGB3BP overexpression and OS were 1.64 (1.29–2.08) in 1948 patients with glioma." (PMID 34953037, 2022). "To compile credible results, we further used the data in the GEO dataset to compare the expression levels of ITGB3BP in glioma tissues and normal tissues." (PMID 34953037, 2022). "In this study, we investigated the biological function of ITGB3BP in glioma and its relationship with survival prognosis for the first time." (PMID 34953037, 2022). "The TIMER database analysis results revealed a correlation between the expression of ITGB3BP and the infiltration of various immune cells in glioma." (PMID 34953037, 2022). "We also analysed the expression level of ITGB3BP protein in glioma using immunohistochemistry (IHC) data." (PMID 34953037, 2022).
glioma (continued). "ITGB3BP was up‐regulated and had a strong predictive value in the 3‐ and 5‐year outcomes of glioma in the CGGA‐Seq (AUC > 0.7), CGGA microarray (AUC > 0.8) and TCGA‐Seq datasets (AUC > 0.8)." (PMID 34953037, 2022). "In the gene co‐expression analysis, we found many genes co‐expressed with ITGB3BP in glioma, which play a potential role in malignant progression." (PMID 34953037, 2022). "This is the first study to reveal the relationship between ITGB3BP and glioma, to the best of our knowledge." (PMID 34953037, 2022). "The expression level of ITGB3BP in secondary and recurrent glioma was significantly higher than that in primary glioma." (PMID 34953037, 2022). "For the first time, we revealed a high expression level of ITGB3BP in glioma from the GEPIA, GEO and HPA databases." (PMID 34953037, 2022). "Hence, we believe that the overexpression of ITGB3BP plays a critical role in the poor prognosis of glioma patients." (PMID 34953037, 2022). "Our findings provide the first evidence that ITGB3BP is a glioma oncogene that can affect the survival time of patients through the cell cycle and other signalling pathways; thus, targeting ITGB3BP may be a promising treatment strategy." (PMID 34953037, 2022). "Collectively, we discovered multiple tumour‐related signalling pathways via GSEA, which suggests that ITGB3BP may be involved in the tumourigenesis of glioma through these pathways." (PMID 34953037, 2022). "Thus, ITGB3BP is a potential new biomarker that can be used for the clinical diagnosis and treatment of glioma." (PMID 34953037, 2022). "Some small‐molecule drugs were identified, such as hexestrol, which may specifically inhibit ITGB3BP and be useful in the treatment of glioma." (PMID 34953037, 2022). "Collectively, these findings provide new insight into the role in glioma of ITGB3BP, which might serve as a potential biomarker and novel therapeutic target for diagnosis and treatment." (PMID 34953037, 2022). "Therefore, we collected thousands of tissue samples from multiple databases for comprehensive analysis to reveal the regulatory effect of ITGB3BP in the pathological process of glioma." (PMID 34953037, 2022). "Hence, we believe that the high expression of ITGB3BP is a powerful predictor of good survival and prognosis in patients with glioma." (PMID 34953037, 2022). "In this study, we confirmed that ITGB3BP could lead to a poor prognosis of glioma, but the regulatory effect of ITGB3BP overexpression on the cell signalling pathway needs to be further elucidated." (PMID 34953037, 2022). "Finally, to further validate the changes in the mRNA expression level of ITGB3BP in glioma, we used RT‐qPCR to verify the expression of ITGB3BP in glioma cell lines (T98, U251 and A172) and tissues." (PMID 34953037, 2022). "ITGB3BP may be an oncogene that affects the pathological process of glioma, but the specific mechanism still needs to be further explored." (PMID 34953037, 2022). "In general, these observations indicate that the mRNA expression level of ITGB3BP in glioma tissues is significantly up‐regulated, suggesting that ITGB3BP may act as a tumour promoter and play a significant role in tumourigenesis." (PMID 34953037, 2022). "Despite the growing recognition of ITGB3BP as an essential feature of various cancers, the relationship between ITGB3BP and glioma remains unclear." (PMID 34953037, 2022). "Finally, we used GSEA and TIMER database analysis to explore the possible mechanism of ITGB3BP in glioma and identified potential therapeutic compounds that may target ITGB3BP by CMap analysis." (PMID 34953037, 2022). "Due to the abnormally high expression of ITGB3BP in glioma tissues, we then explored whether there is a relationship between the expression level of ITGB3BP and clinical features related to the prognosis of glioma." (PMID 34953037, 2022). "Therefore, this study aimed to analyse the clinical and prognostic effects of ITGB3BP on glioma." (PMID 34953037, 2022).
glioma (continued). "RNA‐Seq and microarray data from 2222 glioma patients were included, and we found that the expression level of ITGB3BP in glioma tissues was significantly higher than that in normal brain tissues." (PMID 34953037, 2022). "Second, our analysis results showed that the expression level of ITGB3BP was closely related to a series of important clinical features of glioma, and survival analysis showed that increased expression of ITGB3BP was not conducive to the survival of patients." (PMID 34953037, 2022). "However, the effect of ITGB3BP on the immune microenvironment in GBM is relatively limited compared with that in LGG, probably because of the large amount of heterogeneity between GBM and LGG, although both are glioma subtypes." (PMID 34953037, 2022). "However, to date, there are no studies on the relationship between ITGB3BP and glioma or the biological function of ITGB3BP in glioma." (PMID 34953037, 2022). "However, since no previous studies have reported the relationship between high ITGB3BP expression and survival time in glioma patients, we could not incorporate any published data into the meta‐analysis." (PMID 34953037, 2022).
ovarian carcinoma (3 papers, 2019 to 2022). A malignant neoplasm originating from the surface ovarian epithelium. "Overexpression of ITGB3BP was demonstrated to decrease the proportion of side population (SP) cells which were harboring malignant phenotypes in ovarian cancer." (PMID 33974527, 2021). "In summary, using a functional genomics screen, we identified six novel genes, MSL3, ZNF691, VPS45, ITGB3BP, TLE2, and ZNF498, that regulate the proportion of SP cells in ovarian cancer." (PMID 31578411, 2019). "Using another ovarian cancer clinical dataset, (GSE3149), the survival for patients with tumors having low expression of MSL3 and ITGB3BP was again significantly shorter than that of the high expression group (p < 0.05 for each)." (PMID 31578411, 2019). "In this study, we identified six novel genes, MSL3, ZNF691, VPS45, ITGB3BP, TLE2, and ZNF498 whose expression altered the proportion of the SP cells of ovarian cancer cells through a functional genomics screen." (PMID 31578411, 2019). "In conclusion, through a functional genomics screen using an shRNA library we identified six novel genes; MSL3, ZNF691, VPS45, ITGB3BP, TLE2 and ZNF498, whose downregulation individually increased the proportion of SP cells and the malignant phenotypes of ovarian cancer." (PMID 31578411, 2019).
schizophrenia (2 papers, 2019 to 2022). A major psychotic disorder characterized by abnormalities in the perception or expression of reality. "SNPs associated with schizophrenia risk were identified in the gene ITGB3BP." (PMID 35215271, 2022).
autism (1 paper, 2022). Persistent deficits in social interaction and communication and interaction as well as a markedly restricted repertoire of activity and interest as well as repetitive patterns of behavior. "The upregulated ITGB3BP gene in the present study is targeted as an autism-risk gene in human fetal brains, and also differential expression was observed in a mouse model." (PMID 35215271, 2022). "Overall, the literature on the ITGB3BP, DDR1, and MMP8 genes indicates that the observation regarding the integration of transcriptome and exome genotyping in autism is a notable addition for the understanding of the genetics of autism." (PMID 35215271, 2022).
autism spectrum disorder (1 paper, 2022). A spectrum of developmental disorders that includes autism, and Asperger syndrome. "The integration of significantly up- and downregulated genes and genes of significant SNPs identified regulatory variants (rs6657480, rs3130780, and rs1940475) associated with the up- (ITGB3BP) and downregulation (DDR1 and MMP8) of genes in autism spectrum disorder in people of Arab ancestries." (PMID 35215271, 2022). "Regulatory variations (rs6657480, rs3130780, and rs1940475) identified the up- (ITGB3BP) and downregulation (DDR1 and MMP8) of genes in autism spectrum disorder in patients of Arab ancestry discovered through the integration of up- and downregulated genes and genes of significant genotypes." (PMID 35215271, 2022).
liver cancer (1 paper, 2024). An epithelial or non-epithelial malignant neoplasm that arises from the liver. "We found that upon knockdown of several ligands (VEGFA, ITGB3BP and ADAM9) in M2 macrophages, there was significant reduction in at least one of the liver cancer stem cell markers tested." (PMID 38169544, 2024).
melanoma (1 paper, 2021). A malignant, usually aggressive tumor composed of atypical, neoplastic melanocytes. "The identification of an eQTL with integrin subunit beta 3 binding protein (ITGB3BP) suggest this transcriptional coregulator that binds to and enhances the activity of members of the nuclear receptor families could be important for melanoma risk at 1p31.3." (PMID 34930111, 2021).
skin cancer (1 paper, 2021). "Moreover, in the skin cancer, ITGB3BP was documented to play a dual role: It acts as a tumor suppressor in the early stages of tumorigenesis while acting as a promoter in the progression of cancer." (PMID 33974527, 2021).
Thrombocytopenia (1 paper, 2017). A reduction in the number of circulating thrombocytes. "Finally, the underexpression of ITGB3BP and other RUNX1-regulated genes due to RUNX1 mutations, can cause thrombocytopenia or impaired platelet aggregation and secretion." (PMID 28813466, 2017).
tumor (7 papers, 2019 to 2025). "From the evidence above, it is clear that ITGB3BP, as a pathogenic gene, plays an important regulatory role in the pathological process of a variety of tumours." (PMID 34953037, 2022). "However, the role of different spliced transcript variants of ITGB1BP1 and ITGB3BP in focal adhesions and tumor cell migration remains unclear." (PMID 40731028, 2025). "Prior studies have noted that ITGB3BP affects the occurrence and development of tumours through different signal transduction pathways." (PMID 34953037, 2022). "The results of GSEA suggested that the high ITGB3BP expression group exhibited increased activity of a variety of cellular signalling pathways related to malignant tumour progression." (PMID 34953037, 2022). "ITGB3BP is reported to function as a tumor suppressor in breast cancer." (PMID 31578411, 2019). "Moreover, Nutlin also regulated the tumor-promoting HSF1 targets CDC6, ITGB3BP, RBBP5, BST2, and FBLN1." (PMID 34188043, 2021).
ITGB3BP also shares sentences with these, for which no sentence is quoted: cancer (3 papers); prostate carcinoma (2); anaplastic astrocytoma (1); anaplastic oligoastrocytoma (1); anaplastic oligodendroglioma (1); astrocytoma (1); glioblastoma (1); hepatocellular carcinoma (1); metastatic cancer (1); oligoastrocytoma (1); oligodendroglioma (1); pancreatic cancer (1); Sepsis (1).